CTLA4 (cytotoxic T-lymphocyte associated protein 4)
Diseases named in the same sentence as CTLA4 in open-access papers (continued):
Sharing a sentence is not in itself a finding about the gene and the disease.
enterocolitis (11 papers, 2016 to 2025). An inflammatory process affecting the small intestine and colon. "CTLA-4 inhibitors, particularly tremelimumab and ipilimumab, exhibited the strongest association with enterocolitis." (PMID 40465755, 2025). "PD-1 inhibitors are more strongly associated with upper GI and hepatobiliary inflammatory adverse reactions, whereas CTLA-4 inhibitors carry a higher risk of enterocolitis." (PMID 41221037, 2025). "Treatment of naïve Balb/c mice biweekly with Fc-effector anti-CTLA4 antibody for 7 weeks resulted in weight loss associated with increased intestinal permeability and severe enterocolitis." (PMID 33127658, 2020). "Enterocolitis is particularly frequent and severe following CTLA-4 inhibition, and appears to resemble, and even cause inflammatory bowel diseases." (PMID 32117295, 2020). "Although most GI irAEs are relatively mild, 15–20% of patients receiving CTLA-4 inhibitors and 2–5% of patients receiving PD-1/PD-L1 inhibitors will develop severe enterocolitis, with a smaller fraction progressing to life-threatening inflammation." (PMID 38339253, 2024). "We have developed a mouse model of checkpoint blockade-mediated enterocolitis via prolonged administration of an Fc-competent anti-CTLA4 antibody." (PMID 33127658, 2020). "Correspondingly, CTLA-4 inhibitors (e.g., ipilimumab and tremelimumab)—alone or in combination—are more frequently associated with GI irAEs, such as enterocolitis or hepatitis, as opposed to PD-1/PD-L1 blockade alone." (PMID 38339253, 2024). "In meta-analyses, the occurrence of enterocolitis as an irAE with CPI therapies is shown to be mainly dependent on the type of therapy (more frequent with CTLA-4 antibodies than with PD-1 antibodies), while the localization and the entity of the tumor do not seem to influence the probability." (PMID 38420014, 2024). "Given the importance of CTLA-4-expressing Tregs in maintaining immune homeostasis in the GIT, it is not surprising that therapeutic administration of CTLA-4-targeted MAbs in particular would predispose to development of enterocolitis." (PMID 29623257, 2018). "Thus, we developed a novel model of enterocolitis mediated by anti-CTLA4 treatment in mice." (PMID 33127658, 2020). "Sustained treatment with Fc-effector, but not Fc-mutant or Fc-null, anti-CTLA4 antagonist for 7 weeks resulted in enterocolitis." (PMID 33127658, 2020).
esophageal squamous cell carcinoma (11 papers, 2012 to 2025). Esophageal squamous cell carcinoma (ESCC) is a type of esophageal carcinoma (EC) that can affect any part of the esophagus, but is usually located in the upper or middle third. "This study aimed to assess the possibility of KN046, a bispecific antibody targeting PD-L1 and CTLA-4, combined with chemotherapy and palliative radiotherapy for advanced esophageal squamous cell carcinoma (ESCC)." (PMID 39105827, 2024). "The purpose of this study was to evaluate the prognostic role of the cytotoxic T-lymphocyte-associated antigen-4 (CTLA-4) expression level and the platelet lymphocyte ratio (PLR) level in esophageal squamous cell carcinoma (ESCC) patients." (PMID 31485274, 2019). "Consequently, the development of anti-CD47 antibodies is warranted, and anti-CD47 therapy has been shown to enhance the efficacy of PD-1 and CTLA-4 inhibitors in esophageal squamous cell carcinoma (ESCC)." (PMID 40963868, 2025). "Potentially, checkpoint inhibitors targeting PD-1, PD-L1 and CTLA-4 could counteract immunosuppressive cells populations that dominate the tumor microenvironment in esophageal squamous cell carcinoma." (PMID 38305770, 2024). "Moreover, targeting CD47 in a mouse model of esophageal squamous cell cancer not only enhanced proinflammatory responses and increased infiltration of CD8+ T cells within the tumor, but also increased PD-1 and CTLA-4 expression, thus increasing mouse susceptibility to anti-PD-1 and CTLA-4." (PMID 35053602, 2022). "Using mRNA expression data from TCGA for esophageal SCC and AC, expression of IDO1, PD-1, PD-L1, CTLA-4, Her2, and OX-40 was evaluated." (PMID 29805749, 2018). "In fact, co-expression of CD8 mitigated any negative prognostic implications of CTLA-4 or LAG-3 expression in esophageal squamous cell carcinoma patients." (PMID 39751903, 2025). "Besides, HNSCC, esophageal squamous cell carcinoma and nasopharyngeal cancer (NPC) patients with a higher expression of CTLA-4 had a worse prognosis to those with lower CTLA-4 level." (PMID 31708918, 2019).
experimental autoimmune encephalomyelitis (11 papers, 2014 to 2025). An autoimmune demyelinating disease of the central nervous system that is produced experimentally in animals by the injection of homogenized brain or spinal cord in Freund's adjuvant. "Recently, upfront IL-6 blockade mitigated irAE symptoms in a murine model of experimental autoimmune encephalomyelitis while preserving antitumor activity after anti-CTLA-4 exposure." (PMID 39403935, 2024). "In support of this, Paterson and colleagues showed that Treg cells with conditional ablation of Ctla4 in adult mice remained functionally suppressive and sufficient to protect mice from experimental autoimmune encephalomyelitis." (PMID 37197667, 2023). "Inhibition of these co-stimulatory molecules using CTLA-4-Fc in experimental autoimmune encephalomyelitis, an animal model of MS, has been effective in decreasing inflammation and demyelination, but there are few reports on NMOSD." (PMID 28946890, 2017). "For example, blocking CTLA-4 in a relapsing–remitting experimental autoimmune encephalomyelitis mice model has been shown to exacerbate clinical disease and inhibit clinical remission through enhanced T cell reactivity to epitopes associated with induction and relapse." (PMID 33362680, 2020).
influenza (11 papers, 2014 to 2025). An acute viral infection of the respiratory tract, occurring in isolated cases, in epidemics, or in pandemics; it is caused by serologically different strains of viruses (influenzaviruses) designated A, B, and C, has a 3-day incubation period, and usually lasts for 3 to 10 days. "In this context, a reduction in the humoral immunogenicity to pneumococcal and influenza vaccine has been shown in CTLA-4-Ig-treated patients." (PMID 35309297, 2022). "The risk gene PPP2R5A is mainly involved in Influenza Infection, protein localization to membrane, PID IGF1 PATHWAY, CTLA4 inhibitory signaling, Platelet activation, signaling and aggregation, and Hemostasis." (PMID 33014188, 2020). "The observed impact of activated iNKT cells on the phenotype and functionality of lung and splenic ILC1s as well as the implication of CTLA-4 expression for ILC1 responsiveness also raised the question of whether CTLA-4 expression by ILC1s is affected in the course of influenza infection." (PMID 31440243, 2019). "To observe the correlation of CRP with the local immune response of lung in mice to influenza infection, we quantified the relative expression levels of 6 immune checkpoint mRNAs in lung tissues of mice, including GITR, BTLA, TIM-3, PD-1, CTLA-4, and LAIR-1." (PMID 36275680, 2022). "The transient activation of CD69+ T cells, peaking at day 3, without sustained elevation of PD-1/CTLA-4, challenges the paradigm of “vaccine exhaustion” observed in frequent revaccination against influenza." (PMID 40746539, 2025). "Influenza infection alone did not impact the expression density or frequencies of CTLA-4+ ILC1s as compared to uninfected controls, whereas prior iNKT cell stimulation by αGalCerMPEG induced significantly enhanced frequencies of CTLA-4+ ILC1s as well as increased expression density levels." (PMID 31440243, 2019).
mucosal melanoma (11 papers, 2015 to 2025). A melanoma that arises from a mucosal site. "Herein is described the case of a 79-year-old woman with metastatic mucosal melanoma and bone marrow infiltration causing disseminated intravascular coagulation, who was treated with an immunotherapy combination (anti-CTLA-4 and anti-PD-1 antibodies), achieving complete disease remission." (PMID 34659846, 2021). "Results have shown that using a combination of PD-1 and CTLA-4 inhibitors has a greater response of 37.1% versus 23.3% in PD-1 inhibitor therapy alone in patients with mucosal melanoma." (PMID 39006602, 2024). "ICI such as Programmed cell death protein 1 (PD-1) and cytotoxic T-lymphocyte-associated protein 4 (CTLA-4) inhibitors are well-established substances in the treatment of CMM and show activity in mucosal melanoma as well." (PMID 37272953, 2023). "An 82 year old male presented with widespread metastatic mucosal melanoma and was initially treated with the CTLA-4 inhibitor ipilimumab but had progression of disease after four doses." (PMID 26885370, 2016). "Furthermore, emerging strategies such as neoadjuvant and combination immunotherapies (e.g., anti-PD1 with anti-CTLA4) hold promise in managing locally advanced or metastatic mucosal melanomas." (PMID 40003600, 2025). "Thus, different research groups tried to investigate combination of immunotherapy such as anti-PD1 or anti-CTLA4 antibodies with irradiation in mucosal melanoma." (PMID 39650062, 2024). "A multicenter retrospective study conducted in France revealed that in 151 patients with mucosal melanoma, treatment with anti-CTLA-4 or anti-PD-1 antibodies provided an ORR of 11.9% (95% CI, 7.2–18.2) and a median OS of 15.97 months (interquartile range, 6.89–27.11 months)." (PMID 34149718, 2021).
myelodysplastic syndrome (11 papers, 2017 to 2024). A clonal hematopoietic disorder characterized by dysplasia and ineffective hematopoiesis in one or more of the hematopoietic cell lines. "In a study in myelodysplastic syndrome, a high level of PD-L1, PD-L2, PD-1 and cytotoxic T lymphocyte associated antigen 4 (CTLA4) expression was observed in patients treated with decitabine." (PMID 31258527, 2019). "This study was designed in order to identify the prognostic relevance of CD200 expression and soluble Cytotoxic T-lymphocyte antigen-4 (CTLA-4) levels in myelodysplastic syndrome (MDS) patients." (PMID 32856848, 2020). "Early data from clinical trials did show marginal clinical response in myeloid malignancies, such as AML or myelodysplastic syndrome (MDS), when using mAbs targeting CTLA4 or PD-1/PD-L1 as single agents." (PMID 38060328, 2024).
oral cancer (11 papers, 2014 to 2025). "In the document on association of CTLA4 SNP with risk of tobacco-related oral carcinoma in high-risk North Indian population, TACAG appeared as susceptible haplotype with TACGA and TATAG, while TACGG and CACGG appeared as protective haplotypes." (PMID 25667935, 2015). "A clinical analysis conducted for oral cancer showed that CTLA4 can enhance the therapeutic efficacy of anti-PD-1 immunotherapy." (PMID 36185403, 2022). "The low expression of three ICGs positively correlated with CD274 (BTLA, CD27, and CTLA4) indicated a better prognosis compared to their high expression, indicating their coinhibitory roles in the tumor immunology of oral cancer." (PMID 35127742, 2021).
oral squamous cell carcinoma (11 papers, 2013 to 2025). "In a phase II trial (NCT03799445), the combination therapy of anti‐PD‐1 and anti‐CTLA‐4 antibodies with RT is being investigated for patients with HPV‐positive oral squamous cell carcinoma." (PMID 39170944, 2024). "Evidence has also found that miR-138-5p can exert multiple anti-tumor effects and immunostimulatory effects by targeting PD-1 and CTLA-4 in oral squamous cell carcinoma." (PMID 36765782, 2023). "Another study showed that VISTA was overexpressed in oral squamous cell carcinoma and correlated with other immune checkpoint markers PD-L1 and CTLA-4." (PMID 30057891, 2018). "AhR also plays a central role in IFNγ-induced expression of IDO1, PD-L1, CTLA-4, LAG-3, and CD39 in an oral squamous cell carcinoma model." (PMID 38632994, 2024). "These checkpoints play important role in oral squamous cell carcinoma progression and some checkpoints such PDL1, PD1 and CTLA4 are being used in immunotherapy with promising results, reinforcing the role of the tumor microenvironment in cancer progression." (PMID 38219446, 2023).
autoimmune myocarditis (10 papers, 2019 to 2024). Autoimmune myocarditis is an autoimmune disease that affects the heart. "Of note, prior studies have shown that PD-1 and PD-L1 are constitutively expressed in mouse and human cardiomyocytes and that CTLA-4 and PD-1 deletions are associated with autoimmune myocarditis in mice." (PMID 36318537, 2022). "Previous genetic knockout studies in mice have shown that loss of immune checkpoint protein function can cause cardiac problems; deficiency of CTLA-4 in mice is associated with a severe autoimmune myocarditis whilst PD-1 or PD-L1 deficient mice are susceptible to autoimmune myocarditis." (PMID 39081368, 2024). "Similarly, CTLA-4-deficient mice also developed autoimmune myocarditis with infiltration of CD4+ and CD8+ T lymphocytes in the myocardium." (PMID 37493228, 2023). "Additionally, several animal studies proved that PD-1 and CTLA-4 deficiencies predispose the animal to autoimmune myocarditis with a fatal outcome." (PMID 36142866, 2022). "Spatial transcriptomics, single‐cell RNA sequencing, and flow cytometry are used to decipher how anti‐cytotoxic T lymphocyte antigen‐4 m2a antibody (anti‐CTLA‐4 m2a antibody) aggravated cardiac injury in experimental autoimmune myocarditis (EAM) mice." (PMID 38978328, 2024). "It is known that the interaction between CTLA-4 on Th17 cells and B7 inhibits Th17 differentiation and suppresses Th17-mediated autoimmune myocarditis in mice." (PMID 31747403, 2019). "Based on early animal models, it was demonstrated that after CTLA-4 inhibition or PD-1 deletion, autoimmune myocarditis may develop." (PMID 36079112, 2022). "Deletion of the CTLA-4 and PD-1 axis led to autoimmune myocarditis, which suggests that PD-1/PDL1 and CTLA-4 play important roles in limiting T-cell-mediated autoimmune myocarditis." (PMID 37493228, 2023). "That is, the lack of CTLA-4 and PD-1 leads to autoimmune myocarditis, suggesting that PD-1/PD-L1 and CTLA-4 play an important role in limiting T cell-mediated autoimmune myocarditis." (PMID 36110551, 2022).
cholangiocarcinoma (10 papers, 2015 to 2025). A carcinoma that arises from the intrahepatic biliary tree (intrahepatic cholangiocarcinoma) or from the junction, or adjacent to the junction, of the right and left hepatic ducts (hilar cholangiocarcinoma). "Cholangiocarcinomas exhibit expression of the immune checkpoint molecules, programmed cell death ligand 1 (PD-L1), and cytokine T-lymphocyte–associated protein 4 (CTLA-4), in the tumor microenvironment." (PMID 38004310, 2023). "They found that high CTLA4 expression, representing the enrichment of Treg cells, in adjacent tissue is associated with the poor recurrence free survival of cholangiocarcinoma." (PMID 34055632, 2021). "Recent successes of immune checkpoint inhibitors, such as anti-PD-1/PD-L1 and anti-CTLA-4, in a variety of human malignancies, have led to increased research interest in the function of the immune microenvironment during cholangiocarcinoma development and progression." (PMID 36551593, 2022). "In addition, NCT03849469, which was previously discussed relative to HCC, is also investigating a bispecific antibody for CTLA-4 and LAG-3 for intrahepatic cholangiocarcinoma." (PMID 34440865, 2021). "Similarly, in another randomized trial, 128 patients with advanced cholangiocarcinoma underwent standard chemotherapy in combination with the PD‐L1 inhibitor, either with or without the CTLA4 inhibitor." (PMID 38059559, 2023). "For instance, cholangiocarcinoma (CCA) cells with positive PD-1 and CTLA-4, have been reported to form immunosuppressive TME by decreasing the amount of cytotoxic immune cells, increasing the amount of Tregs and making tumor-infiltrating T cells to express receptors of PD-1 and CTLA-4." (PMID 41024300, 2025).
Granuloma (10 papers, 2009 to 2025). A compact, organized collection of mature mononuclear phagocytes, which may be but is not necessarily accompanied by accessory features such as necrosis. "In IMH caused by anti-CTLA-4, a pattern of granulomatous hepatitis, with fibrin-ring granulomas and central-vein endothelitis is found." (PMID 38398187, 2024). "LI due to CTLA-4 is considered to be characterized by granulomatous hepatitis, including fibrin ring granulomas and central vein endotheliitis, and LI due to PD-1/PD-L1 is considered to be characterized by lobular hepatitis." (PMID 38667461, 2024). "On the other hand, there were nine cases of LI with CTLA-4, three of which showed granuloma, supporting previous reports." (PMID 38667461, 2024). "In the present study, granuloma was found in 5 of 37 patients (14%), 3 of which were treated with combination therapy, including CTLA-4." (PMID 38667461, 2024). "In a subset of granulomas, we evaluated the expression of exhaustion markers CTLA-4 and PD-1 on T cells." (PMID 25611466, 2015). "Some evidence also suggests that CD4+ Th1-like cells may contribute to the formation of granulomas, and anti-CTLA-4 therapy has been shown to increase the amounts of peripheral Th17 CD4+ cells that produce the proinflammatory cytokine IL-1720." (PMID 34413300, 2021). "In fact, the pathology caused by S. japonicum egg infection is considered to be a Th2-type immune response; accordingly, the granuloma diameter was shown in the present study to be significantly increased in the anti-CTLA-4 mAb and combination compared to the infected-control group." (PMID 31134084, 2019). "We demonstrated that primary single-sex infection with female but not male S. mansoni cercariae decreases granuloma size and hepatic fibrosis, and is accompanied by a Ctla4-mediated suppression of TH2 hyperreactivity." (PMID 28542175, 2017). "Our limited data on T cell exhaustion markers (CTLA-4 and PD-1) did not support an inverse correlation with the cytokine response from granulomas." (PMID 25611466, 2015). "Consistent with our findings in peripheral blood of humans, expression of the inhibitory receptors CTLA-4, PD-1, and LAG-3 was very low on T cells isolated from granulomas of Mtb-infected macaques and did not correlate with Mtb bacterial load." (PMID 31497018, 2019).
lymph node metastasis (10 papers, 2013 to 2026). "At 15 months after diagnosis, she received radiotherapy due to nasopharynx and supraclavicular lymph node metastasis as well as treatment with a bispecific antibody targeting PD-1 and CTLA-4, cadonilimab, combined with chemotherapy." (PMID 41768248, 2026). "In our study, among six CTLA-4 positive cases, five had lymph node metastasis, and one patient died of the disease; however, due to the limited number of positive cases in our study, the findings are not conclusive." (PMID 39286684, 2024). "Like KRAS, it is noted that CTLA-4 expression was also higher in patients with lymph node metastasis, advanced pathological stages (72.7% vs. 50.0%), and MSI-stable cancer (68.4% vs. 25.0%)." (PMID 37761948, 2023). "A high CTLA-4/CD3-ratio was linked to absent lymph node metastases (p = 0.0295) and to PD-L1 positivity on immune cells (p = 0.0026)." (PMID 35091676, 2022). "Similarly, ICI effectiveness, including PD1, CTLA4, and TIGIT, was higher in the group with lymph node metastasis than in the non‐metastasis group." (PMID 39206584, 2024). "ICI marker analysis indicated that the lymph node metastasis group exhibited non‐significant differences in immune checkpoint gene expression levels, except for PD1, TIGIT, and CTLA4, which were significantly higher than those in the non‐metastasis group (p = 0.0008, p = 0.0004, p = 0.0093)." (PMID 39206584, 2024).